ABCG8 (ATP binding cassette subfamily G member 8)
Diseases named in the same sentence as ABCG8 in open-access papers (continued):
Sharing a sentence is not in itself a finding about the gene and the disease.
dyslipidemia (8 papers, 2012 to 2025). "Possible mechanisms linking GD and CVD include dyslipidemia, chronic inflammation and abnormalities in the ABCG8 cholesterol transporter gene." (PMID 30967586, 2019). "Many factors, such as analytical methods, gender, Apo E phenotype, ABCG8/G5 phenotype, diabetes mellitus, metabolic syndrome and dietary intake can affect the circulating PS concentrations." (PMID 22412917, 2012). "The phenotype of FH is also affected by other genes, including ATP-binding cassette subfamily G member 5 (ABCG5), ATP-binding cassette subfamily G member 8 (ABCG8), and apolipoprotein E (APOE), which are known to be causal genes of recessive types of inherited dyslipidemia." (PMID 38540356, 2024). "HSD administration possibly protects from dyslipidemia through the downregulation of fatty acid synthase (FAS) and acetyl coenzyme A carboxylase alpha (ACCα), and upregulation of ATP-binding cassette transporters G8 (ABCG8) protein expressions in the liver." (PMID 40672362, 2025). "In addition, variants in genes causing other dyslipidemias showing phenotypes overlapping with FH may mimic FH in patients without causative variants (FH-phenocopies; ABCG5, ABCG8, CYP27A1 and LIPA genes) or act as phenotype modifiers in patients with a pathogenic variant in a causative gene." (PMID 36834635, 2023).
cholelithiasis (7 papers, 2022 to 2025). The presence of crystallized deposits forming in the gallbladder or biliary tree, primarily composed of cholesterol, bilirubin, and bile. "Common mutations in ABCG8 confer most of the genetic risk for cholelithiasis, accounting for approximately 25% of the total risk." (PMID 39519421, 2024). "According to this study, low phytosterols in childhood promoted the occurrence of cholelithiasis in adults in carriers of the risk variant 19H of the ABCG8 gene." (PMID 36362164, 2022). "The prioritized genes for the individual index lipid variants significantly associated with cholelithiasis in the PheWAS analysis include ABCG8, a hepatic cholesterol transporter, responsible for the efflux of cholesterol from the enterocytes to the lumen and from the hepatocytes into bile." (PMID 36575460, 2022). "Seven genes, including GCKR, SNX17, ABCG8, MARCH8, FUT2, APOH, and HNF1A, were revealed to be colocalized with the causal signal between sphingomyelin and cholelithiasis." (PMID 40428345, 2025). "Genetic colocalization study identify one SNP locating at the ABCG5/ABCG8 locus is shared by both campesterol and cholelithiasis, indicating the potential therapeutic target in preventing cholesterol gallstone formation." (PMID 38347599, 2024). "To further clarify whether this association might be driven by the ABCG8 gene alone, we excluded from the LDL-PGS all variants within the locus and tested the association between LDL-PGS and cholelithiasis in the UK Biobank." (PMID 36575460, 2022). "In pediatric patients with cholesterol and pigment gallstones, RNA expression of ABCG5 and ABCG8 measured by quantitative real-time reverse transcription polymerase chain reaction (qRT-PCR) showed increased levels in patients with cholelithiasis than in healthy controls." (PMID 36362164, 2022).
Insulin resistance (7 papers, 2013 to 2025). Increased resistance towards insulin, that is, diminished effectiveness of insulin in reducing blood glucose levels. "Our findings support previous studies that have identified the upregulation of Abcg5 and Abcg8 in response to insulin resistance and an HF diet." (PMID 30526554, 2018). "Specifically, hepatic insulin resistance leads to the activation of the forkhead transcription factor (FoxO1), which promotes the overexpression of bile cholesterol transport proteins Abcg5 and Abcg8, resulting in excessive cholesterol secretion into bile." (PMID 39944962, 2025). "In hepatocytes, insulin resistance induces abnormal expression of the transcription factor forkhead box protein O1 (FOXO1) through the ABCG5 and ABCG8 genes to promote cholesterol secretion." (PMID 37396166, 2023). "In patients with diabetes, hepatic insulin resistance (IR) could promote CG formation by upregulating the expression of hepatic ABCG5 and ABCG8." (PMID 38268006, 2024).
hyperlipidemia (6 papers, 2020 to 2024). "Second, alternative causes of hyperlipidemia should be considered—four unique P and LP variants in other genes (CYP27A1, ABCG5, ABCG8, and LIPA) were found in seven patients (2% of all patients with positive monogenic variant), which increases the overall diagnostic yield to 23.6%." (PMID 39769230, 2024).
lipid metabolic disorder (6 papers, 2020 to 2026). "The search for rare variants (gnomAD frequency less than 1 %) in the ABCA1, ABCG1, ABCG5, ABCG8 and NPC1L1 genes was performed using targeted sequencing data for 169 patients with lipid metabolism disorders." (PMID 42253452, 2026). "The aim of this work was to study the spectrum of rare variants in the cholesterol transporter genes ABCA1, ABCG1, ABCG5, ABCG8 and NPC1L1 that occur in patients with lipid metabolism disorders in the population of the Northwestern region of Russia." (PMID 42253452, 2026). "This review focuses on the regulation of lipid metabolism disorders by the gut microbiota through the effects of bile acids (BA), short-chain fatty acids (SCFAs), bile salt hydrolase (BSH), and genes such as ABCG5 and ABCG8, FXR, NPC1L, and LDL-R." (PMID 33005189, 2020).
coronary artery disease (5 papers, 2020 to 2023). "They demonstrated that individuals carrying the risk genotype for both ABCG8 variants had an increased risk of cardiovascular disease (RR 1.57, 95% CI 1.13–2.18; p = 0.01) and coronary heart disease (RR 1.72, 95% CI 1.23–2.41; p = 0.002)." (PMID 35096999, 2021). "Briefly, a genetic score of ABCG5/ABCG8, variants which predict a 1 mmol/L (39 mg/dL) increase in non-HDL-C, is associated with 2-fold increase in risk of coronary heart disease (CHD) [odds ratio (OR) 2.01, 95% confidence interval (CI) 1.75–2.31]." (PMID 36837764, 2023).
cholestasis (4 papers, 2013 to 2018). Impairment of the bile flow caused by obstruction within the liver, or outside the liver in the bile duct system. "Moreover, mutations in Baat, Abcg5 or Abcg8 have been shown to be involved in the development of cholestasis in humans." (PMID 24112857, 2013). "Thus, the down-regulation of ABCG2 and ABCG8 may involve in the disruption of bile acid and cholesterol homeostasis during cholestasis." (PMID 25798860, 2015).
fatty liver disease (4 papers, 2017 to 2023). A reversible condition wherein large vacuoles of triglyceride fat accumulate in liver cells via the process of steatosis. "For example, mice deficient in ABCG5 and ABCG8 are prone to the development of fatty liver disease and liver injury." (PMID 30679232, 2019). "Animal studies also showed that mice with ABCG5/G8 deficiencies may cause hypertriglyceridemia via multiple metabolic pathways and that sterol transportation via ABCG5 and ABCG8 opposes the development of fatty liver disease and loss of glycemic control independently of phytosterol accumulation." (PMID 36981027, 2023). "In addition, NCEH1, ABCG5, and ABCG8 are reported to be drug targets of pioglitazone and ezetimibe in the therapy of human gallbladder cholesterolosis and HFD-induced fatty liver." (PMID 29464180, 2017). "Thus, FGF19 and NGM282 appear to selectively modulate LXR signaling, upregulating canonical LXR target genes (Abcg5, Abcg8, Scarb1, Srebf1, Fasn, Scd1, Srebf2, and Scap) without inducing hepatic steatosis." (PMID 30679232, 2019).
Obesity (4 papers, 2015 to 2023). Accumulation of substantial excess body fat. "These genes include CD36 (HDL-C), RPTOR (obesity) and ABCG5/ABCG8 (low-density lipoprotein cholesterol (LDL-C) and total cholesterol)." (PMID 26021296, 2015). "Notably, the absence of ABCG5/ABCG8 (ATP binding cassetteG5/G8) reduces biliary cholesterol secretion and results in hepatic cholesterol accumulation, acceleration of obesity, and exacerbation of NAFLD in mice." (PMID 29769539, 2018).
type 2 diabetes (4 papers, 2013 to 2025). "A SNP of ABCG8 was associated with fasting plasma glucose levels in a cross-sectional study but did not predict hyperglycemia or incident type 2 diabetes." (PMID 23840693, 2013).
xanthoma (4 papers, 2021 to 2026). A non-neoplastic disorder characterized by a localized collection of histiocytes containing lipid. "Patients were categorized based on the presence of xanthomas and the type of variants in the ABCG5 or ABCG8 genes." (PMID 39860331, 2025). "Among the 8 patients who carried ABCG8 variations, xanthomas were present in the majority (6, 66.7%) of individuals, and arthritis, growth restriction, and local thickening of the bilateral carotid arteries were found in 2 (22.2%) patients each." (PMID 38509578, 2024).
breast carcinoma (3 papers, 2019 to 2020). "Down-regulation of ABCG8 was observed in breast carcinoma after chemotherapy." (PMID 31683902, 2019). "Expression of ABCG8 was downregulated in tumors of breast cancer patients compared to non-neoplastic control tissues, but the role of germline polymorphism is unclear." (PMID 33334016, 2020).
Cholecystitis (3 papers, 2018 to 2024). The presence of inflammatory changes in the gallbladder. "Previous studies have shown that ABCG8 expression is elevated in patients with cholesterol gallstone disease and cholecystitis, and our study further demonstrated that ABCG8 also plays a role in the development of non-calculous cholecystitis." (PMID 39519421, 2024).
Hyperglycemia (3 papers, 2013 to 2023). An increased concentration of glucose in the blood. "In a Finland cohort study, genetic variations in ATP binding cassette subfamily G member 8 (ABCG8) were associated with fasting blood glucose (FBG) levels but did not foresee the risk of T2DM, whereas cholesterol metabolism markers were significantly associated with hyperglycemia and T2DM." (PMID 37686841, 2023). "The major allele of the most significant SNP, rs4299376 of ABCG8, was nominally associated with elevated levels of FPG at baseline, but did not predict the development of hyperglycemia in a 5-year follow-up study." (PMID 23840693, 2013).
hypertriglyceridemia (3 papers, 2022 to 2023). A laboratory test result indicating elevated triglyceride concentration in the blood. "In the present study, in a prediabetic HHTg model with severe hypertriglyceridemia we observed markedly increased expression of Abcb1b, Abca1, and Abcg8 genes and decreased expression of Abcb1a and Abcg5 genes." (PMID 37077818, 2023).
colitis (2 papers, 2021 to 2023). Inflammation of the colon. "However, interestingly, the expression of genes involved in cholesterol excretion such as ABCG5, and ABCG8 was not changed, while the expression of BSEP, a major bile acid transporter, was significantly decreased in the liver of FMT-colitis mice compared to that of FMT-control group." (PMID 36735734, 2023).
iron overload (2 papers, 2017 to 2020). "P34 had UH and iron overload, and variations in 3 genes: a homozygous p.H63D variation in HFE, which may contribute to iron overload even though its implication is not totally clear, a heterozygous ABCG8 VUS and 2 heterozygous ADAMTS13 VUS." (PMID 32641076, 2020).
liver cancer (2 papers, 2019 to 2024). An epithelial or non-epithelial malignant neoplasm that arises from the liver. "To corroborate the data, we also evaluate the expression of NR1H3, ABCG5 and ABCG8 in four different GEO datasets of human liver cancer, observing a significant reduction of their level in tumour tissue compared to non-tumoral one." (PMID 38824560, 2024). "Besides, the suppression of ABCG8 induced the apoptosis of liver cancer by inhibiting doxorubicin efflux." (PMID 31683902, 2019).
arrhythmogenic right ventricular cardiomyopathy (1 paper, 2021). "According to the test results, cousins (IV:1 and IV:2) have the same variants in ABCG8 (intronic), CTNNA3, and RASA1 genes, involved in the pathogenesis of arrhythmogenic right ventricular cardiomyopathy (CTNNA3) and RASA1 (capillary malformations, Park Weber syndrome)." (PMID 33829027, 2021).
autoimmune disease (1 paper, 2014). A disorder resulting from loss of function or tissue destruction of an organ or multiple organs, arising from humoral or cellular immune responses of the individual to their own tissue constituents. "In principle, somatic repeat mutations could induce the production of aberrant ABCG8 protein variants that would be immunogenic, as previously argued for autoimmune disease." (PMID 24988487, 2014).
cardiomyopathy (1 paper, 2021). A disease of the heart muscle or myocardium proper. "Father (III:4) and aunt (III:3) had the same variants in genes: ABCG8, BIN1, SCN2B, and SYNE1 (related to Emery-Dreifuss muscular dystrophy with cardiomyopathy, cardiac conduction defects, and cerebellar ataxia)." (PMID 33829027, 2021).
cholesterol metabolism disorder (1 paper, 2022). "Moreover, it could improve intestinal cholesterol metabolism disorder induced by high-fat and high-cholesterol diets via the reduction of the expression of HMGCR, NPC1L1, ACAT2, MTP, ASBT and IBABP mRNA or protein, increasing ABCG8 mRNA expression." (PMID 36816874, 2022).
Infertility (1 paper, 2017). "For ABCG8 and KSR2, animal models provide further support as gene expression deficiency can cause infertility in females (ABCG8,) and males (KSR2,)." (PMID 28640878, 2017).
migraines (1 paper, 2023). "In contrast, ABCG5/ABCG8 enhancement, APOB inhibition, NPC1L1 inhibition, PCSK9 inhibition was found to be suggestively associated with higher risk of migraine." (PMID 37596566, 2023). "Our findings suggested the possibility, without confirmation, that exposure to bile acid sequestrants targeting ABCG5/ABCG8, cholesterol absorption inhibitors targeting NPC1L1, and Mipomersen targeting APOB might increase the likelihood of migraines in individuals." (PMID 37596566, 2023).
primary biliary cirrhosis (1 paper, 2019). "In addition, seladelpar, a selective PPARβ/δ agonist, modulated the reversed cholesterol transporter ABCG5/ABCG8 during primary biliary cirrhosis treatment." (PMID 31336903, 2019).
psoriasis (1 paper, 2023). An autoimmune condition characterized by red, well-delineated plaques with silvery scales that are usually on the extensor surfaces and scalp. "Given a bile acid imbalance has been observed in patients with psoriasis and psoriatic arthritis and the role of ABCG5/8 in the TICE, we speculate whether ABCG5 and ABCG8 play a role in the bile acid metabolism of psoriasis." (PMID 37234169, 2023).
Sepsis (1 paper, 2021). Sepsis is defined as life-threatening organ dysfunction caused by a dysregulated host response to infection. "Similarly, hepatic expression of transporters involved in export of cholesterol to bile and gut (Abcg5 and Abcg8) was unaffected by sepsis or 3HB supplementation." (PMID 34274000, 2021).
steatosis (1 paper, 2021). Increased lipid within the cytoplasm of cells. "Given the similarities between developing liver and iHLC in global gene expression, gene set enrichment, and downregulation of ABCG8, the susceptibility to steatosis with immaturity was tested in iHLC exposed to an exogenous plant sterol, stigmasterol (represented as StigAC in figures)." (PMID 34117281, 2021).
Stroke (1 paper, 2024). Sudden impairment of blood flow to a part of the brain due to occlusion or rupture of an artery to the brain. "Next, using multitrait GWAS analysis (MTAG) on ACD and the prioritized traits (CAD, stroke, WMH), we identified intronic SNPs in SMG6 and ABCG8 to be GW significant (pMTAG < 1.67E‐08, for three phenotypes) for ACD." (PMID 39046104, 2024).
cardiovascular disease (4 papers, 2009 to 2023). "Previous studies have shown that the ABCG8 D19H (rs11887534) variant is associated with gallstone disease history, cancer derived from biliary tract, lipid profile, and cardiovascular diseases." (PMID 36981027, 2023).
tumor (4 papers, 2021 to 2024). "Compared with metastatic tumor tissues, the expression of ABCG8 and LOXL4 was higher, whereas that of PDE1B was lower, which was concordant to our findings using the TCGA database." (PMID 33564309, 2021). "The upregulation of ABCG8 plays a pivotal role in tumor development and defines disease prognosis." (PMID 33564309, 2021). "Since vitamin K3 functions as an anti-tumor agent and cisplatin—an anticancer drug—resistant cells were also resistant to vitamin K3 treatment, ABCG5/ABCG8 may play a role in resistance of cancer cells to vitamin K3 cytotoxicity." (PMID 36839356, 2023).
ABCG8 also shares sentences with these, for which no sentence is quoted: diabetes (5 papers); genetic disorder (4); cancer (3); Macrothrombocytopenia (3); Alzheimer disease (2); Hepatic steatosis (2); Hypertension (2); Xanthelasma (2); acalculous cholecystitis (1); acute pancreatitis (1); Arthritis (1); bladder (1); capillary malformation (1); central obesity (1); cerebellar ataxia (1); congenital generalized lipodystrophy type 2 (1); coronary atherosclerosis (1); Dubin-Johnson syndrome (1); Emery-Dreifuss muscular dystrophy (1); endotoxemia (1); familial chylomicronemia syndrome (1); gallbladder cancer (1); gallbladder cholesterolosis (1); gastric cancer (1); Giardia infection (1); Gilbert syndrome (1); glaucoma (1); hyperalphalipoproteinemia (1); hypobetalipoproteinemia (1); infection (1).
A further 15 diseases each share a sentence with ABCG8 in 1 paper.